BMX (BMX non-receptor tyrosine kinase)
Diseases named in the same sentence as BMX in open-access papers (continued):
Sharing a sentence is not in itself a finding about the gene and the disease.
tauopathy (1 paper, 2021). Neurodegenerative disorders involving deposition of abnormal tau protein isoforms (tau proteins) in neurons and glial cells in the brain. "Therefore, the molecular mechanism by which ibrutinib's off‐targets (e.g., EGFR, JAK3, BMX) modulate tauopathy will be explored in a future study." (PMID 33709472, 2021).
tumor (27 papers, 2010 to 2025). "Tumorigenesis study in vivo showed that knockdown of BMX significantly diminished tumor growth in immuno-deficient mice." (PMID 28514765, 2017). "In tumor cells, where the ROS levels are already highly elevated and antioxidant defenses are often dysregulated and overloaded, Mn porphyrins like BMX-001 cause excess H2O2 accumulation and lead to increased tumor cell death." (PMID 40872550, 2025). "As already indicated in Section 1, the higher the levels of BMX-001 and the higher the oxidative stress, the higher is the oxidative damage to tumor proteins." (PMID 40900760, 2025). "Clinically, low miR-495 or high ETK/BMX levels correlated with advanced tumor stage and shorter patient survival." (PMID 41465138, 2025). "BMX-001 has also been shown to oxidize the p50 subunit of NF-κB, thereby suppressing tumor progression while protecting normal cells from chemoradiation-induced damage." (PMID 40872550, 2025). "HG6-64-1 and QL-XII-47 were excluded due to low target gene upregulation in GBM and undetectable BMX expression in tumor samples." (PMID 40563807, 2025). "Taken together, these observations identify BMX as an attractive therapeutic candidate for different tumor types, with potential roles in tumor growth, differentiation, and response to therapy." (PMID 39133652, 2024). "Matched transcriptional and chromatin H3K4me3 profiling of primary nMNA NB models identifies BMX as a marker of tumor xenografts and spheroids." (PMID 39133652, 2024). "Based on these observations, we decided to assess the effect of depleting BMX expression on the tumor-initiation properties of these models." (PMID 39133652, 2024). "Consistent with our analyses, BMX mRNA expression levels were increased in NB tumor and spheroid models, and the gene TSS showed higher H3K4me3 deposition when compared with adherent cultures." (PMID 39133652, 2024). "Next, we set out to interrogate the potential involvement of BMX in supporting the functional properties of our primary tumor models." (PMID 39133652, 2024). "Although global BMX transcript levels remained relatively low across all tumor types analyzed, as expected for a marker of undifferentiated tumor subpopulations, NB tumors ranked seventh in terms of BMX expression." (PMID 39133652, 2024). "BMX expression correlated with high tumor stage and poor patient survival and was crucial to the maintenance of the self-renewal and tumorigenic potential of NB spheroids." (PMID 39133652, 2024). "To further validate the clinical relevance of our findings, we also interrogated 2 NB transcriptomic data sets for BMX expression levels across different tumor stages." (PMID 39133652, 2024). "In the presence of DHEA, an FDA approved Bruton’s tyrosine kinase (BTK) and BMX inhibitor, zanubrutinib, effectively blocked androgen receptor–positive (AR-positive) xenograft tumor growth in castrated mice." (PMID 36647834, 2023). "EGFR wild type is associated with decreased expression of BMX/SOX9 and inadequate pericyte coverage in neovascularization, and such an incomplete vascular system exacerbates tumor tissue hypoxia and necrosis." (PMID 34566988, 2021). "BMX is suggested to function as a tumor promoter, inhibiting chemotherapy- and radiotherapy-induced apoptosis in colorectal cancer." (PMID 31130822, 2019). "With the aim to explore the role of BMX-ARHGAP in tumor formation and growth, the stable transfected SGC7901 cells were delivered into the nude mice." (PMID 31130822, 2019). "The Tec kinase BMX non-receptor tyrosine kinase (BMX) has been shown a tumor promoting role in gliolastoma multiforme through mediation of self-renewal and growth, and the neurotrophic tyrosine receptor kinase 2 (NRTK2) in precursor growth and differentiation." (PMID 30064387, 2018). "A few studies have correlated BMX function with tumor growth, metastasis or poor prognosis in cancer." (PMID 28422715, 2017).
tumor (continued). "In this study, we first reported that BMX can promote cell proliferation and tumor progression through the PI3K/AKT/mTOR and STAT3 pathways." (PMID 28514765, 2017). "It is possible that the chimeric transcript active the BMX mediation of tumorigenicity in GCA patients since BMX has been suggested to promote tumor growth and metastasis other cancers." (PMID 25499959, 2014). "Finally, BMX inhibitors readily reversed this cellular state, increased the sensitivity of NB spheroids toward chemotherapy, and partially reduced tumor growth in a preclinical NB model." (PMID 39133652, 2024). "Consistent with the results obtained in our primary tumor models, SK-N-AS spheroids also showed a marked decrease in viability, proliferation, and sphere-forming capacity upon BMX depletion." (PMID 39133652, 2024). "From a translational perspective, it is tempting to speculate that BMX inhibition could synergize with current standard of care and targeted therapies to eradicate the most aggressive tumor subpopulations in advanced and refractory NB." (PMID 39133652, 2024). "Hence, BMX was systematically characterized across 33 TCGA tumor types through the analysis of gene expression, which was further validated using various datasets to confirm our gene expression findings." (PMID 39347140, 2024). "This may be particularly relevant in light of BMX expression by endothelial cells and the role played by this kinase in enhancing tumor angiogenesis through the PI3K/Akt angiogenic signaling pathway, independent of VEGF." (PMID 39133652, 2024). "BMX depletion decreases the tumor initiation properties of NB spheroids." (PMID 39133652, 2024). "However, our in vivo results using both shRNA and pharmacological agents tend to confirm that BMX depletion/inhibition within a complex tumor ecosystem still leads to substantial decrease in tumor growth, supporting the translational relevance of our findings." (PMID 39133652, 2024). "Thus, consistent with the in vivo results obtained using shRNA lentiviral vectors, pharmacological inhibition of BMX also results in reduced NB1 tumor growth and prolonged mice survival." (PMID 39133652, 2024). "However, the mechanisms downstream of BMX, effects on tumor metabolism, and the context for contributions to CRPC have remained elusive." (PMID 36647826, 2023). "The nuclear localization of BMX appears to be specific to ECs (this study) and tumour cells." (PMID 31642192, 2020). "Either BMX or ARHGAP alone has been determined to drive tumor development." (PMID 31130822, 2019). "RGD-peptide treatment of mice with established intracerebral GBM xenografts significantly reduced the percentage of Sox2-positive tumor cells and CSCs in close proximity to ECs, decreased integrin αvβ3 and BMX activation and p130CAS phosphorylation in the ECs, and reduced the vessel surface area." (PMID 27270311, 2016). "In summary, we have identified a previously unrecognized integrin αvβ3/bFGF initiated signaling event in the perivascular niche in GBM, involving EC contact with CSCs or tumor cells that requires BMX for activation of p130CAS and promotes chemotactic migration of ECs and thereby angiogenesis." (PMID 27270311, 2016). "Similarly, we used the GSE84984 dataset for COAD validation, in which seven tumor samples and six normal samples were used; the analysis revealed that 70,523 DEGs, 29908 downregulated, and 8685 upregulated, and BMX within the downregulated genes (logFC= -0.367636, adj.P.Val= 1.63E-05)." (PMID 39347140, 2024). "Given the current need for cell state–specific targeted therapies in NB tumors, we explored the possibility that BMX expression, in addition to support the undifferentiated state of NB tumor cells, may also be involved in the establishment/maintenance of these divergent tumor cell identities." (PMID 39133652, 2024).
tumor (continued). "It would also be interesting to spatially resolve the distribution of BMX-expressing cells in primary human NB tumors across different stages and to assess if BMX is preferentially expressed in any defined location within the tumor, similar to the perivascular BMX+ niches observed in GBM." (PMID 39133652, 2024). "First, BMX inhibitors have the ability to reverse the MES phenotype, which has been associated with increased resistance to multiple therapies and may increase tumor sensitivity to selected agents." (PMID 39133652, 2024). "Among the prognostic biomarkers identified for LIHC and KIRC, such as bone marrow kinase (BMX), GAS5 distinguishes itself through its upregulation and context-dependent modulation of the tumor-immune microenvironment." (PMID 39958058, 2025). "BMX transcript levels strongly increased upon PRRX1 expression in this model, confirming a link between tumor cell phenotypes and BMX expression in NB." (PMID 39133652, 2024). "This approach revealed that, in both tumor models, CD44+ NB cells exhibited markedly higher BMX expression levels as compared with their CD44– counterparts." (PMID 39133652, 2024). "Through univariate Cox regression analysis, nine genes, including 3 oncogenes (HTR3C, CRHR2 and AGTR1), 6 tumor suppressor genes (CD8A, CD3E, SERPIND1, CXCR6, BMX and CD247) were proved to be correlated with the overall survival of EC patients." (PMID 38355782, 2024). "Consistent with our in vitro findings, BMX depletion resulted in prolonged survival for mice injected with NB1 spheroid cells, reflecting a marked delay in tumor establishment and growth." (PMID 39133652, 2024). "We found that BMX and FYN had lower expression levels in HCC tumour tissues, whereas KPNA2, PFKFB4, and SPP1 had higher expression levels in HCC tumour tissues." (PMID 36873244, 2023). "Ibrutinib targets the B-cell receptor pathway and immune cells in the tumor microenvironment via BTK, as well as kinases relevant to solid tumor treatment, including tyrosine kinase ETK/BMX and interleukin-2–inducible T-cell kinase (ITK)." (PMID 37296940, 2023). "To explore the possible role of EPHA3 in MDR, we assessed the influence of EPHA3 on chemoresistance, cell cycle, apoptosis, and tumor growth, as well as the relationship between EPHA3 and the expression of PI3K, BMX, and STAT3 in SCLC." (PMID 27101199, 2016). "The fusion gene BMX-ARHGAP was validated using RT-PCR and gel analysis, which was recurrently present in tumor tissues in about 26.7% (4/15) GCA patients." (PMID 25499959, 2014). "The chimeric transcript BMX-ARHGAP was validated and recurrently occurred in 4/15 independent tumor tissues." (PMID 25499959, 2014). "Remarkably, nMNA NB cell lines ranked second across all tumor types in terms of lowest IC50 for QL-XII-47 and exhibited markedly higher sensitivity than MNA NB lines profiled in the same study despite similar BMX expression levels, suggesting a selective dependency of nMNA NB tumors." (PMID 39133652, 2024). "Additionally, the blocking of BMX has been proven to boost the efficacy of chemotherapeutic agents by promoting BAK activation, causing tumor cells to become highly responsive to otherwise non-lethal doses of clinically important chemotherapeutic agents." (PMID 39347140, 2024). "qRT-PCR results showed that the expression levels of BMX and FYN in HCC tumour tissues were significantly lower than those in adjacent normal tissues." (PMID 36873244, 2023). "Following this strategy, in our study, we show for the first time to our knowledge that the nonreceptor tyrosine kinase (TK) BMX is preferentially expressed in undifferentiated NB metastatic cells and regulates their clonogenicity, MES phenotype, and tumor-initiating potential." (PMID 39133652, 2024).
cancer (23 papers, 2009 to 2025). A tumor composed of atypical neoplastic, often pleomorphic cells that invade other tissues. "Upregulation of BMX is implicated in the development of numerous cancers, including Bladder, Renal Cell Carcinoma, Triple Negative Breast Cancer (TNBC), Prostate, and Castration-Resistant Prostate Cancer (CRPC)." (PMID 41213918, 2025). "BMX expression is upregulated in numerous cancers and causes acquired resistance to chemotherapeutic drugs." (PMID 41213918, 2025). "The consistent downregulation of BMX expression observed across multiple cancer datasets underscores the potential utility of this gene as a valuable diagnostic biomarker for these cancers." (PMID 39347140, 2024). "We also noted an age-related increase of transcripts encoding for the Bone marrow kinase on chromosome X (BMX), a cytosolic kinase expressed in different tissues and in several types of cancer." (PMID 27545843, 2016). "Therefore, further investigations are required to elucidate the underlying mechanisms and context-dependent functions of BMX in various cancer types." (PMID 39347140, 2024). "The consistent downregulation of BMX observed across the three datasets in BRCA, COAD, LUAD, LUSC, and READ suggests that BMX may have potential as a diagnostic biomarker for these cancer types." (PMID 39347140, 2024). "Although BMX has emerged as an attractive cancer target, genetic studies revealed that removing BMX kinase activity alone is insufficient to kill the cancer cell, and BMX knockout in mice is viable." (PMID 41213918, 2025). "Knockdown of BMX in cancer cells dramatically potentiates BAK activation following DNA damage, rendering cells hypersensitive to killing by otherwise sub-lethal doses of drug irrespective of the mode of drug action." (PMID 41213918, 2025). "This contributes to the ability of the cancer cell to evade cell death, hence why high BMX overexpression is known to confer resistance to chemotherapeutic agents." (PMID 41213918, 2025). "The study has been mentioned and this study built upon each other to explore the potential of BMX as a target in the fight against cancer." (PMID 39347140, 2024). "Our investigation of BMX gene expression patterns across cancer clinical stages utilized data from the GEPIA which individual cancer stages are based on the TCGA clinical annotation." (PMID 39347140, 2024). "Detailed analyses revealed notable downregulation of BMX in various clinical parameters such as age, gender, race, and cancer stage (all p < 0.05)." (PMID 39347140, 2024). "TIMER database analysis revealed that the expression of BMX was significantly different from that in normal tissue in 16 cancer types." (PMID 39347140, 2024). "This study accommodates several other analyses like clinical parameters, immune cell infiltration, and DNA promoter methylation profiles to evaluate the general role of BMX in several cancers." (PMID 39347140, 2024). "Since there are few direct comprehensive studies linking BMX role with multiple cancers, this study aimed to utilize bioinformatic tools to conduct a comprehensive analysis of BMX across multiple cancers, assessing its potential role." (PMID 39347140, 2024). "Using TCGA samples, this analysis revealed that BMX gene expression was significantly downregulated in several cancer types, including BRCA, COAD, LUAD, LUSC, and READ, compared with normal samples in the TIMER, GEPIA, and UALCAN databases." (PMID 39347140, 2024). "Targeting BMX has been proposed as a strategy for treatment of various diseases including cardiovascular disorders and certain cancers." (PMID 33291717, 2020).
cancer (continued). "The gene BMX nonreceptor tyrosine kinase regulates differentiation and tumorigenicity of several types of cancer cells, and another gene (MLLT11, transcription factor 7 cofactor) was expressed in several leukemic cell lines." (PMID 30793795, 2019). "Up-regulation of BMX expression was found in many cancer types including prostate, breast and colon cancers." (PMID 26909357, 2015). "Most literature, thus far, regards BMX as a modulator of apoptosis and cancer cell growth, and its cell-specific function has been characterized in various cancer cells." (PMID 24860816, 2014). "We previously found that knockdown of BMX sensitized cancer cells to cell death through BAK activation, so we examined whether BMX inhibitors could phenocopy this sensitization to chemotherapeutic agents." (PMID 41213918, 2025). "However, cancer cell survival signalling upregulates BMX activity and phosphorylation of BAK at Y108, meaning the apoptotic threshold is held abnormally high." (PMID 41213918, 2025). "This study evaluates commercially available BMX inhibitors to understand their mechanisms of action and assess whether targeting BMX, either alone or in combination with existing treatments, could improve cancer treatment outcomes." (PMID 41213918, 2025). "Our data show that reducing agents like TCEP and DTT decrease the binding of BMX-IN-1 to BMX, suggesting that the redox state may contribute to drug resistance in cancers." (PMID 41213918, 2025). "BMX has many known substrates whose activity is modulated in cancer due to BMX overexpression." (PMID 41213918, 2025). "Finally, we verified that BMX gene expression in seven cancer samples was consistent according to the TIMER and GEPIA databases using the UACLAN database." (PMID 39347140, 2024). "These contrary results may be due to the different samples used to assess BMX expression; in this study, we used RNA sequences from the TCGA dataset, whereas the previous study utilized cancer cell lines." (PMID 39347140, 2024). "Furthermore, it was significantly upregulated in LUAD (p < 0.0001) and LUSC (p < 0.0001), compatible with BMX expression in these cancers." (PMID 39347140, 2024). "Importantly, our findings of significantly low BMX expression in LUAD and LUSC, along with their methylation profiles suggest that the low expression of BMX across these cancers is due to epigenetic factors." (PMID 39347140, 2024). "BMX is known to participate in various signal transduction pathways, like the Stat pathway, influencing the differentiation and carcinogenicity of different cancer cell types." (PMID 39347140, 2024). "Moreover, to gain a comprehensive understanding of the role of the BMX gene in cancer, we delved into clinical parameters, immune infiltration, methylation profiles, and genetic alterations." (PMID 39347140, 2024). "In the following experiments, we made efforts in examining the regulatory effects that BMX-ARHGAP had on the GC stem cell markers and their properties, and analyzing the potential regulatory network of BMX-ARHGAP/SH2/JAK/STAT3 to provide an anti-cancer target for cancer treatment." (PMID 31130822, 2019). "Moreover, BMX is expressed in several cancers and involved in cell growth, transformation, migration, survival, apoptosis and tumorigenicity." (PMID 28514765, 2017). "BMX expression is altered in a number of different cancers, including those of the breast and prostate, suggesting BMX may play roles in cancers." (PMID 28422715, 2017). "Further studies revealed that the kinase responsible for maintaining BAK in this inactive conformation was a tyrosine kinase called BMX, which has been reported to be upregulated in numerous cancer types including breast cancer, prostate cancer, bladder cancer as well as others." (PMID 27140313, 2016). "BMX was identified in human bone marrow cells, and was demonstrated to have been expressed in myeloid hematopoietic lineages cells, endothelial cells, and several types of cancers." (PMID 27602372, 2014).